TMSB4X (thymosin beta 4 X-linked)
Description:
Plays an important role in the organization of the cytoskeleton. Binds to and sequesters actin monomers (G actin) and therefore inhibits actin polymerization. [Hemoregulatory peptide AcSDKP]: Potent inhibitor of bone marrow derived stem cell differentiation. Acts by inhibits the entry of hematopoietic pluripotent stem cells into the S-phase (By similarity).
Synonyms: TB4X; TMSB4; FX; PTMB4
Tractability: Small molecule: a structure with a bound ligand is known. Antibody: its Gene Ontology location is reachable by antibodies, with high confidence. PROTAC: UniProt records ubiquitination sites on it; ubiquitination databases record sites on it; its protein half-life has been measured.
Gene: Protein-coding gene on chromosome X (12,975,107 to 12,977,227, forward strand). Ensembl gene ENSG00000205542.
Subcellular location: Cytoplasm, cytoskeleton
Subcellular location (Human Protein Atlas): Cytosol; Nucleoplasm; Vesicles
Pathways (Reactome):
Hemostasis: Platelet degranulation
Gene Ontology:
Molecular function: actin monomer binding; actin monomer sequestering activity; enzyme binding; protein binding; protein sequestering activity; RNA binding
Biological process: negative regulation of actin filament polymerization; negative regulation of canonical NF-kappaB signal transduction; negative regulation of inflammatory response; positive regulation of ATP biosynthetic process; positive regulation of blood vessel endothelial cell migration; positive regulation of endothelial cell chemotaxis; tumor necrosis factor-mediated signaling pathway; regulation of cell migration; actin filament organization
Cellular component: cytoplasm; cytosol; extracellular region; nucleus; platelet alpha granule lumen; cytoskeleton
Homologues: Paralogues in human: TMSB4Y (93% identical).
Diseases named in the same sentence as TMSB4X in open-access papers:
TMSB4X is named in the same sentence as 100 diseases in open-access papers, as found by Europe PMC text mining. Sharing a sentence is not in itself a finding about the gene and the disease. The quoted sentences say what the papers report.
melanoma (7 papers, 2019 to 2026). A malignant, usually aggressive tumor composed of atypical, neoplastic melanocytes. "Our results suggest that the silencing of TMSB4X expression in melanoma cells caused changes in their biomechanical properties." (PMID 33807338, 2021). "In summary, the actin cytoskeleton, Nestin, and Vimentin filaments were organized significantly differently in melanoma cells with low Tβ4 levels than the cells with high TMSB4X expression." (PMID 33807338, 2021). "To further validate the tumorigenic potential of melanoma cells with silenced TMSB4X expression, we decided to check in vivo tumor formation using the chorioallantoic membrane (CAM) assay often used for such purposes." (PMID 33807338, 2021). "Using microarrays data we show that both SNAI1 (gene encoding SNAI/Snail) and VIM (gene encoding vimentin) expression levels exhibited positive correlation with TMSB4X expression in human melanoma patients." (PMID 31921836, 2019). "In our study, we analyzed microarray data from melanoma patients and melanoma cell lines, which were characterized by a wide range of TMSB4X expression." (PMID 31921836, 2019). "Here, we demonstrate that also in melanoma cells there is a connection between TMSB4X expression and EMT progression." (PMID 31921836, 2019). "Additionally, we observed that the silencing of TMSB4X expression in melanoma cells affected their adhesion, migration, and invasion abilities." (PMID 33807338, 2021). "In agreement with the differential abundance analysis, APCA+ on the cell type indicates that monocytes are characterized by high intensities of CORO1A, LCP1, TMSB4X, and RPL13, while melanoma cells are characterized by higher intensities of VIM and MCALL1." (PMID 40775377, 2025). "We defined clusters corresponding to melanoma (PMEL, MLANA), immune infiltrates (TRBC2, TRAC, TMSB4X), melanophages (CD74, LYZ), keratinocytes (KRT14, TRIM29), blood vessels (CAVIN1, PECAM), and fibroblast‐enriched areas in the dermis (DCN, COL1A2, FBLN1)." (PMID 39846232, 2025). "A smaller tissue from patient ID 9561, collected in 2008, had four clusters, including melanoma (PMEL, TYRP1), immune cells (TMSB4X, IL32), keratinocytes (KRT10, KRT1, DSG1), and fibroblast areas (COL1A2, COL1A1, DCN)." (PMID 39846232, 2025). "For the malignant melanoma cells, PMEL, IFITM1, HSPA1A, DUSP1, FOS and TMSB4X are the shared driver genes across three subtypes in S4 File." (PMID 38096269, 2023). "Here, we continued the study on the role of Tβ4 in melanoma tumorigenesis using, as previously, the two melanoma cell lines: WM1341D, which is characterized by a low expression of TMSB4X, and A375, which was shown to have a higher expression level of TMSB4X." (PMID 33807338, 2021). "TMSB4X is regulated by TGF-β and facilitated tumor metastasis in melanoma." (PMID 36276140, 2022).
renal fibrosis (7 papers, 2016 to 2024). A final common manifestation of a wide variety of chronic kidney diseases characterized by glomerulosclerosis and tubulointerstitial fibrosis. "Tmsb4x is a peptide that acts to suppress renal fibrosis, and loss of endogenous Tmsb4x accelerates kidney disease." (PMID 38625739, 2024). "The same hypothesis applies to the decreased expression of STMN1, TMSB4X and MYH9 in HK-2 cells under diabetic-like conditions, because: i) STMN1 is a microtubule-destabilizing phosphoprotein whose deficiency in mice has been connected to the development of renal fibrosis." (PMID 32579601, 2020).
diabetes (6 papers, 2014 to 2023). "The podocyte expression of both Tmsb4x and Tmsb10 was reduced in both mice with nephrotoxic nephritis or diabetes compared with healthy animals (P < 0.0001)." (PMID 35842494, 2022).
myocardial infarction (5 papers, 2016 to 2025). Gross necrosis of the myocardium, as a result of interruption of the blood supply to the area, as in coronary thrombosis. "In animal models, exogenous Tmsb4x has beneficial effects in diverse pathologies including myocardial infarction, stroke, dry eye, and inflammatory lung disease, and there are clinical trials assessing Tmsb4x treatment in wound healing and cardioprotection." (PMID 27575556, 2016).
cervical carcinoma (4 papers, 2013 to 2025). A carcinoma arising from either the exocervical squamous epithelium or the endocervical glandular epithelium. "Our results showed that the protein expression of DCP1A and TMSB4X increased in cervical cancer cells in the presence of AS-IV." (PMID 32265995, 2020). "DCP1A and TMSB4X, the two proteins regulating autophagy, increased in cervical cancer cells when treated with AS-IV." (PMID 32265995, 2020). "We also found that AS-IV could target the proteins DCP1A and TMSB4X and induce autophagy in suppressing cervical cancer invasion." (PMID 32265995, 2020). "While DCP1A and TMSB4X may be regarded as targets of AS-IV in the process of autophagy, they also may be regarded as targets in the screening of anticancer compounds used in the treatment of cervical cancer." (PMID 32265995, 2020). "Thus, DCP1A and TMSB4X may be regarded as the targets of cervical cancer treatment." (PMID 32265995, 2020). "A pioneering study demonstrated that AS-IV could suppress the progression of cervical cancer by activating the Atg7/Atg12/LC3 autophagy axis through targeting DCP1A and TMSB4X." (PMID 41155562, 2025). "The results suggested that the progression of AS-IV in the suppression of cervical cancer invasion is related to cell signaling transduction, secondary metabolite biosynthesis, and transmembrane transport, and especially might target DCP1A and TMSB4X." (PMID 32265995, 2020).
colon cancer (4 papers, 2019 to 2024). "TMSB4X has been validated as a therapeutic target in colon cancer stem cells in a previous study." (PMID 38729966, 2024).
colorectal cancer (4 papers, 2014 to 2024). A primary or metastatic malignant neoplasm that affects the colon or rectum. "Thymosin beta-4 (TMSB4X) is overexpressed in pancreatic cancer and was proposed as a biomarker for colorectal cancer." (PMID 39201484, 2024).
glioma (4 papers, 2021 to 2024). A benign or malignant brain and spinal cord tumor that arises from glial cells (astrocytes, oligodendrocytes, ependymal cells). "Using the glioma endothelial cell line U87 it was found that succinylated TAGLN2 recruits and represses the function of thymosin beta 4 X-linked, an inhibitor of actin polymerisation, to initiate cytoskeletal remodelling and glioma migration." (PMID 38213532, 2023). "However, the functional role and underlying mechanism of SMOC1, HIPK2, UBA52, S100A6, PPP1CB, CALD1, and TMSB4X in the occurrence and development of diffuse high-grade gliomas was still unknown." (PMID 39530009, 2024). "Moreover, Thymosin beta-4 (TMSB4X) and CD109, and 14.3.3 and HSP90 alpha could discriminate among other brain tumors and low-grade gliomas plus glyoneuronal tumors/pilocytic astrocytoma, or embryonal tumors/medulloblastoma." (PMID 33469081, 2021).
glomerular disease (4 papers, 2016 to 2023). "Thymosin β4 (Tβ4), a peptide encoded by the TMSB4X gene on the X chromosome, is pleiotropic and has cellular functions that are relevant in glomerular disease." (PMID 37175390, 2023). "In the developing mouse heart, Tmsb4x depletion hinders cell migration and differentiation and interferes with coronary vessel development, whereas Tmsb4x depletion in mouse kidney enhances glomerular disease." (PMID 33310787, 2020). "Thus, we provide the first evidence that endogenous Tmsb4x is critical in the progression of glomerular disease." (PMID 27575556, 2016). "To assess whether the downregulation of Tmsb4x and Tmsb10 mRNA in podocytes is also evident in other mouse models of glomerular disease, we analysed the scRNAseq datasets obtained from glomeruli of mice with nephrotoxic nephritis or BTBR ob/ob (LeprOb/Ob) mice with diabetic kidney disease." (PMID 35842494, 2022). "Therefore, we investigated whether Tmsb4x has a role in glomerular disease." (PMID 27575556, 2016). "However, in an experimental model of NTS nephritis, glomerular disease was exacerbated in mice lacking Tmsb4x accompanied by changes in the distribution of podocytes within the glomerulus, increased periglomerular macrophage accumulation, and enhanced fibrosis." (PMID 27575556, 2016).
lung carcinoma (4 papers, 2012 to 2023). "High expression of TMSB4X is contributed to poor prognosis and predicts the metastasis in lung carcinoma." (PMID 37910161, 2023). "The down-regulated RPSA, RPL9, TMSB4X and TUBA1B in normal lung (DDD1) were significantly up-regulated in lung cancer (DDD2)." (PMID 23122428, 2012). "However, seven genes selected from FSL (FOXA2, C4BPA, SCGB3A1, DDX58, CCNDBP, TMSB4X, and CXCL17), and one gene selected from both FSL as well as RSL (CD9), were up-regulated in the lung cancer tissues, but not significantly (P > 0.05)." (PMID 23374247, 2013).
breast carcinoma (3 papers, 2017 to 2024). "The identified PBMC biomarkers (TMSB4X, HSPA4, S100A9, SRSF6, THBS1, CUL4A, and CANX) were significantly upregulated in the breast cancer patients at the metastatic stage compared to both the primary stage and healthy individuals (p < 0.001)." (PMID 32793473, 2020). "TMSB4X, SRSF6, and THBS1 displayed high connectivity degree values among the human protein–protein interaction networks according to the topological analysis, introducing these proteins as potential signatures in PBMCs of breast cancer patients." (PMID 32793473, 2020). "Western blot data indicated that miR-1 overexpression significantly downregulated WASF2, TWF1, CNN3, TMSB4X and CORO1C, showing that miR-1 could inhibit breast cancer cell metastasis by targeting the WASF2, TWF1, CNN3, TMSB4X and CORO1C genes." (PMID 28159933, 2017).
COVID-19 (3 papers, 2021 to 2022). A disease caused by infection with severe acute respiratory syndrome coronavirus 2. "The potentially protective protein thymosin beta-4 is, in humans, encoded by the TMSB4X gene and found on the X chromosome, where it escapes X-inactivation and could thereby help to explain a genetic advantage in COVID-19." (PMID 36359231, 2022).
lupus nephritis (3 papers, 2016 to 2025). Glomerulonephritis in the context of systemic lupus erythematosus. "A similar pattern was also observed for DDX5, B2M, and TMSB4X in CKD/lupus nephritis, and for GATM in the control group." (PMID 39974940, 2025). "However, we found that whole-mouse kidney Tmsb4x mRNA levels were unchanged with NTS nephritis, and this was mirrored when we assessed TMSB4X mRNA levels in glomerular and tubulointerstitial extracts from human kidneys affected by rapidly progressive glomerulonephritis or lupus nephritis." (PMID 27575556, 2016). "Furthermore, in kidney biopsy specimens obtained from patients with either rapidly progressive glomerulonephritis or lupus nephritis, there was no change in glomerular or tubulointerstitial TMSB4X mRNA levels compared with living donor control kidneys." (PMID 27575556, 2016).
non-small cell lung carcinoma (3 papers, 2017 to 2025). A group of at least three distinct histological types of lung cancer, including non-small cell squamous cell carcinoma, adenocarcinoma, and large cell carcinoma. "TMSB4X encodes thymosin beta-4, a well-known secreted small peptide, which is identified as a novel prognostic marker for non-small cell lung cancer." (PMID 38729966, 2024). "Additionally, in non-small cell lung cancer, TMSB4X promotes immune evasion by regulating dendritic cell activity and the tumor immune microenvironment." (PMID 41315466, 2025).
ovarian carcinoma (3 papers, 2019 to 2021). A malignant neoplasm originating from the surface ovarian epithelium. "Another proposed mechanism is the upregulation of the Thymosin Beta 4X-Linked (TMSB4X) expression in ovarian cancer cells." (PMID 34440886, 2021). "The study is aimed at investigating the role of TMSB4X when ADSCs promote ovarian cancer's growth and the underlying mechanisms involved in the study." (PMID 31781249, 2019). "After confirming that ADSCs induced TMSB4X expression in ovarian cancer cells, we subsequently studied the underlying mechanism." (PMID 31781249, 2019). "A proteomic profile of ovarian cancer cells demonstrated an increase in TMSB4X expression in ovarian cancer cells after exposure to an ADSC-conditioned medium." (PMID 34440886, 2021). "ADSC-mediate enhanced expression of TMSB4X promoted ovarian cancer growth and metastasis both in vitro and in an animal model." (PMID 34440886, 2021). "We performed a set of xenograft experiments to examine the role of TMSB4X in the effects of ADSCs on promoting ovarian cancer growth in vivo." (PMID 31781249, 2019). "Next, the effects of ADSCs on promoting ovarian cancer growth were investigated and the role of TMSB4X was determined in this process." (PMID 31781249, 2019). "Identifying the mechanisms by which ADSCs increase TMSB4X expression in ovarian cancer cells needs further studies." (PMID 31781249, 2019). "Compared with cells cultured with normal medium, TMSB4X was expressed at much higher levels in the ovarian cancer cells treated with ADSC CM (all P < 0.001)." (PMID 31781249, 2019). "The qRT-PCR was used to assess the mRNA levels, and western blotting was used to evaluate the levels of the TMSB4X protein in the ADSC CM-treated ovarian cancer cells." (PMID 31781249, 2019). "In this study, TMSB4X is identified as a differentially expressed protein in ovarian cancer cells after ADSC treatment." (PMID 31781249, 2019). "In conclusion, ADSCs promote the proliferation, migration, and invasion of ovarian cancer cells at least partly by increasing TMSB4X expression in ovarian cancer cells." (PMID 31781249, 2019). "TMSB4X inhibition canceled the pro-metastatic effects of ADSCs on ovarian cancer cells." (PMID 34440886, 2021). "Additionally, compared with normal culture medium, ADSC CM substantially increased TMSB4X expression in ovarian cancer cells." (PMID 31781249, 2019). "Taken together, ADSCs may accelerate ovarian cancer cell's proliferation, migration, and invasion by increasing TMSB4X expression." (PMID 31781249, 2019). "TMSB4X expression in ovarian cancer cells may be regulated with the ADSC-secreted IL-1/6, but more studies are required to confirm these findings." (PMID 31781249, 2019). "Moreover, in vitro and in vivo, the effect of ADSCs on promoting tumour proliferation, migration, and invasion was suppressed by TMSB4X knockdown in ovarian cancer cells." (PMID 31781249, 2019). "Based on our results, the ovarian cancer-promoting effects of ADSCs may be at least partially attributed to the expression of TMSB4X in ovarian cancer cells." (PMID 31781249, 2019). "Based on these data, ADSCs induced ovarian cancer cells to overexpress TMSB4X." (PMID 31781249, 2019). "Thus, ADSCs promoted ovarian cancer's growth and metastasis and a blockade of TMSB4X expression reversed this effect." (PMID 31781249, 2019). "However, the protein expression of ovarian cancers cells has been compared with protein expression following treatment ASCs, revealing that thymosin beta 4 X-linked (TMSB4X) accelerated ASC-mediated proliferation, invasion, and migration of ovarian cancer cells." (PMID 32726947, 2020). "Thus, we studied the role of TMSB4X in the effect of ADSCs on promoting ovarian cancer growth." (PMID 31781249, 2019). "In the present study, TMSB4X expression was regulated by ADSCs, forming a TME that is favourable for ovarian cancer metastasis." (PMID 31781249, 2019).
ovarian carcinoma (continued). "Based on our findings, increased TMSB4X expression may play a role in accelerating the ADSC-mediated proliferation, invasion, and migration of ovarian cancers." (PMID 31781249, 2019). "Next, we examined the TMSB4X's role in ovarian cancer cell migration and invasion after treatment with or without ADSC CM." (PMID 31781249, 2019). "As shown in the bioluminescence images captured in vivo, increased ovarian cancer's growth and metastasis, along with elevated TMSB4X expression, were observed in the group of ADSC-conditioned medium, and the tumour-promoting effect of ADSCs was attenuated by the inhibition of TMSB4X." (PMID 31781249, 2019). "A protein expression analysis in ovarian cancer cell lines treated with or without ADSC CM showed that compared to the cancer cells cultured with normal medium, TMSB4X is expressed at approximately 2.7-fold higher levels in the ADSC CM group." (PMID 31781249, 2019).
pulmonary hypertension (3 papers, 2014 to 2024). Increased pressure within the pulmonary circulation due to lung or heart disorder. "Circ-TMSB4X (0003416) (Thymosin Beta 4 X-Linked) was demonstrated to be a potential diagnostic biomarker in children with pulmonary arterial hypertension (PAH) that was caused by CHD." (PMID 39272989, 2024).
brain tumors (2 papers, 2020 to 2021). "Also, the most promising biomarkers for the discrimination between LGG plus GT and PA were TMSB4X and CD109, while the most promising biomarkers for the discrimination between EMB MB and all the other brain tumors were 14.3.3 (YWHA-Z,G,E) and HSP90 alpha." (PMID 33469081, 2021).
gastric cancer (2 papers, 2017 to 2021). A primary or metastatic malignant neoplasm involving the stomach. "In this context, the miR-1-mediated downregulation of the TMSB4X, CNN3, TWF1, CORO1C and WASF2 genes led to the inhibition of tumor cell metastasis of breast and gastric cancers." (PMID 28159933, 2017). "In the present investigation, miR-1 was shown to simultaneously inhibit tumor growth and metastasis of breast and gastric cancers by synchronously targeting CDK4 and TMSB4X, CNN3, TWF1, CORO1C and WASF2 genes." (PMID 28159933, 2017).